NFKB1 (nuclear factor kappa B subunit 1)
Diseases named in the same sentence as NFKB1 in open-access papers (continued):
Sharing a sentence is not in itself a finding about the gene and the disease.
gastritis (76 papers, 2013 to 2025). Inflammation of the stomach. "Overall, Nfkb1−/− mice developed progressive gastric pathology, including gastritis, oxyntic atrophy, dysplasia, and invasive gastric cancer in both the gastric body (corpus) and antrum." (PMID 40673273, 2025). "Having demonstrated that Nfkb1−/− mice developed spontaneous gastritis with mucosal atrophy, we investigated the effects of short-term H. felis colonization on the gastric mucosa of mice with specific NF-κB sub-unit deletions." (PMID 23975431, 2013). "In this study, Nfkb1−/− mice developed the most pathology, with uninfected mice demonstrating spontaneous gastritis and gastric atrophy by 12 months of age." (PMID 23975431, 2013). "Deletion of Tnf in Nfkb1−/− mice significantly reduced the development of gastritis, atrophy, dysplasia, and invasion from 6 to 18 months, with notable suppression of gastric pathology observed through 28 months, although not to the extent seen with Stat1 deletion." (PMID 40673273, 2025). "In Nfkb1−/− mice, gastritis and oxyntic atrophy were observed by 6 months of age." (PMID 40673273, 2025).
endometrial cancer (74 papers, 2010 to 2026). Primary or metastatic malignant neoplasm involving the endometrium (mucous membrane that lines the endometrial cavity). "The decrease in the expression of miR-572, accompanied by the overexpression of NFKB1 observed in our study, may indicate a different regulatory mechanism in endometrial cancer." (PMID 37233761, 2023). "In addition, for TNF-α, NFKB1, and TAB2, all comparisons within endometrial cancer grades were also significant." (PMID 37233761, 2023).
squamous cell carcinoma (74 papers, 2008 to 2025). A carcinoma arising from squamous epithelial cells. "For NFKB1 rs1585215, patients with squamous cell carcinoma (SCC) patients carrying the GG genotype had significantly shorter PFS times." (PMID 35899106, 2022).
glaucoma (73 papers, 2008 to 2025). Increased pressure in the eyeball due to obstruction of the outflow of aqueous humor. "This study identified IL18, TLR9, NFKB1, HDAC4, FKBP2, and KITLG as hub genes in glaucoma that are gut microbiota-related as well as showed that the regulation of immune response by gut microbiota is associated with glaucoma." (PMID 37605653, 2023). "This increase in Nfkb1 observed in the young retinas could have derived from activation of the immune/inflammatory response in glaucoma." (PMID 24146536, 2013). "Alternatively, we performed immunohistochemical analysis of optic nerve slices from human donor tissue, which validated the activation of p50/NFKB1 and p65/c-REL subunits in glaucoma." (PMID 19426536, 2009). "NFKB1, TLR9, and HDAC4 were predicted to be upregulated in glaucoma and their mRNA level increased according to the RT-qPCR data, meanwhile, IL18 was predicted to be downregulated in glaucoma and its mRNA level was also increased according to RT-qPCR." (PMID 37605653, 2023).
sarcopenia (68 papers, 2011 to 2026). Progressive decline in muscle mass due to aging which results in decreased functional capacity of muscles. "The results of the logistic regression analysis showed that the INS/INS genotype of the NFkB1 polymorphism (rs28362491) increased the risk of sarcopenia compared to the other genotypes (OR: 2.943; 95% CI: 1.301–6.654)." (PMID 34683186, 2021). "We believe that the results of association of the NFKB1 gene polymorphism (rs28362491) with sarcopenia observed in the present study can also be found in other Brazilian regions, respecting the constitutional characteristics of populations between regions." (PMID 34683186, 2021). "In conclusion, the NFkB1 gene variant (rs28362491) was associated with the risk of developing sarcopenia in elderly people in the Amazon." (PMID 34683186, 2021). "In the world, as it is a germline structural variant, similar results of this association of NFKB1 gene polymorphism (rs28362491) with sarcopenia can be found, considering that this polymorphism has already been described in non-Brazilian populations." (PMID 34683186, 2021). "Therefore, individuals homozygous for this insertion in the NFkB1 gene have an approximately three-fold increased risk for the development of sarcopenia." (PMID 34683186, 2021). "Therefore, the aim of this study was to investigate possible associations between NFkB1 gene polymorphism (rs28362491) and susceptibility to sarcopenia in the elderly people in the Amazon." (PMID 34683186, 2021). "The NFkB1 pathway is not only activated in aging, but directly contributes to age-related pathologies such as sarcopenia." (PMID 34683186, 2021).
cardiomyopathy (67 papers, 2009 to 2026). A disease of the heart muscle or myocardium proper. "Furthermore, we showed that different genes involved in cardiomyopathies like emerin (EMD), nuclear factor of kappa light polypeptide gene enhancer in B-cells 1 (NFKB1) are under the control of specific miRNAs." (PMID 24699212, 2014).
coronary artery disease (67 papers, 2009 to 2025). "The rs28362491 ins/del variation of the NFKB1 gene is linked to a higher likelihood of MI and increased severity of coronary artery disease." (PMID 39712244, 2024). "Several studies have reported that NFKB1 gene rs28362491 polymorphism was associated with susceptibility to coronary heart disease in populations of different genetic backgrounds." (PMID 35831800, 2022). "More recently, a functional ATTG ins/del polymorphism in the NFKB1 5’-regulatory region modulating NFKB1 protein levels has been related to the risk of coronary heart disease and risk of multiple cancers." (PMID 25615575, 2015). "In a number of studies, including our previous studies, it has been shown that gene polymorphism at the -94 position of the NFKB1 gene promoter region is associated with the susceptibility to coronary heart diseases in populations of different genetic backgrounds." (PMID 35831800, 2022). "Our previous study reported that mutant DD genotype of NFKB1 gene in HUVECs reduced total p50 subunit expression versus wild-type cells and it may be the mechanism of NFKB1 gene polymorphism increase the risk and severity of coronary artery disease (CAD)." (PMID 30910844, 2019).
lung diseases (65 papers, 2010 to 2026). "Of those with significant lung disease, 12 subjects had a TACI variant, 4 had NFKB2, 4 had NFKB1 and 3 others had PI3KCD variants." (PMID 38274105, 2023).
cognitive decline (64 papers, 2014 to 2026). "In this study, we used a mouse model of genetically enhanced NF‐κB activity (nfκb1−/−), characterized by low‐grade chronic inflammation and premature aging, to investigate the impact of inflammaging on cognitive decline." (PMID 32915495, 2020).
tuberculosis (64 papers, 2004 to 2026). A chronic, recurrent infection caused by the bacterium Mycobacterium tuberculosis. "The “MAPK Signaling Pathway” includes genes like MAP3K2, PLA2G4A, and NFKB1, Lastly, the “Tuberculosis” pathway involves IFNGR2, ITGB2, and IL12B." (PMID 40621499, 2025).
malaria (62 papers, 2008 to 2025). Malaria is a serious and sometimes fatal disease caused by a parasite that commonly infects a certain type of mosquito which feeds on humans. "For example, we observed that NFKB1 expression was downregulated after malaria relative to baseline." (PMID 24743880, 2014).
Cirrhosis (61 papers, 2011 to 2026). A chronic disorder of the liver in which liver tissue becomes scarred and is partially replaced by regenerative nodules and fibrotic tissue resulting in loss of liver function. "Upregulation of the downstream signaling in experimental cirrhosis and ACLF were confirmed by qPCR for Fcer1g and Nfkb1." (PMID 32733451, 2020).
head and neck cancer (61 papers, 2007 to 2025). A primary or metastatic malignant neoplasm affecting the head and neck. "The role of the NFKB1 gene rs28362491 polymorphism and NFKBIA gene rs2233406 polymorphism in the development of head and neck cancer (HNC) remains controversial." (PMID 31612070, 2019).
lupus nephritis (59 papers, 2012 to 2026). Glomerulonephritis in the context of systemic lupus erythematosus. "RELA and NFKB1 mutations have been identified in patients with lupus nephritis." (PMID 38772735, 2024).
Salmonella Infections (58 papers, 2004 to 2025). Infections with bacteria of the genus SALMONELLA. "For the G2 group, the main pathways were: Salmonella infection (NFKB1, TJP1, DYNC2H1), transcriptional misregulation in cancer (MET, MLLT1, NFKB1), and adherens junction (MET, TJP1)." (PMID 36012418, 2022).
schizophrenia (55 papers, 2011 to 2025). A major psychotic disorder characterized by abnormalities in the perception or expression of reality. "In the schizophrenia group, the genotyping study of the promoter region of the NFκB1 gene found that the insertion allele was higher than the deletion allele and the ins/ins genotype was higher in frequency than the del/del and ins/del genotypes." (PMID 35619863, 2022). "A genome-wide association study identified NFKB1 to play crucial role in etiology of treatment refractory schizophrenia in the Chinese Han population." (PMID 33080834, 2020). "Transcription factor activity analysis also revealed a panel of seventeen transcription factors with more significant activity in males; NFKB1, FOS, and KLF6 had been linked to schizophrenia previously, although none had been specifically linked to male schizophrenic patients." (PMID 39068467, 2024).
myocarditis (53 papers, 2009 to 2025). Myocarditis is a condition that is characterized by inflammation of the heart muscle (myocardium). "The F15-NOD Nfκb1 heterozygote and homozygote mice, which are considered at risk of developing myocarditis, were found to have an increased risk of myocarditis after influenza hemagglutinin (HA) or HBV vaccination." (PMID 35740465, 2022). "Our findings revealed that the risk of spontaneous myocarditis was slightly higher in male F15 NOD Nfκb1 homozygote mice (95%, 19/20) than in female F15 NOD Nfκb1 homozygote mice (75%, 15/20)." (PMID 35740465, 2022). "In this study, we report that NOD Nfκb1 heterozygote mice can be used for investigating the risk of myocarditis development after vaccination." (PMID 35740465, 2022). "Based on these findings, F15-NOD Nfκb1 heterozygote and homozygote mice are at risk of developing myocarditis." (PMID 35740465, 2022). "Surprisingly, the majority of NOD Nfκb1 homozygote mice were found to die by the eighth week of life because of severe myocarditis." (PMID 35740465, 2022). "Based on the pathological diagnosis tests and serum cTnT results, a small proportion of infant mice with F15 NOD Nfκb1 heterozygote are suspected to have mild myocarditis but mature normally like the F15 NOD Nfκb1 wild-type mice." (PMID 35740465, 2022). "However, the incidence of myocarditis in NOD Nfκb1 heterozygote mice was low in both males and females (15% for males and 5% for females)." (PMID 35740465, 2022). "Additionally, CTLs subpurified from PBS-inoculated F15-NOD Nfκb1 heterozygote mice have been shown to be activated and proliferated via IL-12 stimulation, which reportedly enhanced myocarditis, indicating that the BrdU cell proliferation ELISA kit is working properly." (PMID 35740465, 2022). "Furthermore, in F15-NOD Nfκb1 heterozygote mice, vaccination with influenza HA or hepatitis B virus (HBV) vaccine resulted in an increase in serum cardiac troponin T (cTnT), which is a risk factor for myocarditis, with no gender difference." (PMID 35740465, 2022).
colorectal tumor (52 papers, 2003 to 2024). "For example, NFκB1-/- mice develop fewer colorectal tumors, indicating that NFκB1 acts as a tumor promoter." (PMID 35896012, 2022). "In this study, Nfkb1−/− mice displayed fewer colorectal tumours and increased expression of IL-12 and CXCL-10, supporting the idea that p50 homodimers repress these genes in macrophages, orchestrating their pro-tumorigenic phenotype." (PMID 30205516, 2018).
cholestasis (49 papers, 2013 to 2025). Impairment of the bile flow caused by obstruction within the liver, or outside the liver in the bile duct system. "Among them, HSP90AA1, TLR4, MMP2, APP, and NFKB1 were the crucial targets of FTA in the treatment of cholestasis." (PMID 37432229, 2023). "Molecular docking data revealed a relatively higher binding ability of FTA with TLR4 and NFKB1, suggesting that FTA was a key component in the treatment of cholestasis by RAIs." (PMID 37432229, 2023).
emphysema (49 papers, 2009 to 2025). "Nevertheless, other organs have also been implicated in the premature aging of Nfkb1−/− mice as exemplified both by our results and the early emphysema and decreased skin thickness noted by others." (PMID 25553648, 2014).
acne (48 papers, 2013 to 2026). An inflammatory process of the sebaceous glands which is characterized by comedones, nodules, papules and/or pustules on the skin. "PPAR-γ, TNF, IL-1β, IL-6, TLR and NFκB1 were identified as potential core targets of GA in the regulation of acne vulgaris." (PMID 38792208, 2024). "A total of 37 potential targets were predicted by network pharmacology, among which TNF, IL-1B, IL-6, ESR1, PPARG, NFκB1, STAT3, and TLR4 may be the key targets of GA in the treatment of acne." (PMID 38792208, 2024).
kidney inflammation (47 papers, 2007 to 2025). "We tested the function of NF-κB1 in an acute (nephrotoxic serum (NTS) nephritis) and a chronic (unilateral ureteric obstruction (UUO)) model of renal injury using NF-κB1 (nfκb1−/−) knockout mice." (PMID 28617440, 2017). "Likewise, similar results were obtained when comparing the haplotype frequencies of NFKB1 and NFKBIA between IgAV patients with and without nephritis." (PMID 41208975, 2025).
E. coli infection (46 papers, 2012 to 2026). "Our results highlighted the increased expression of the RIGI gene, which is one of the molecules responsible for the transcription factor NFKB1 pathway activation in E. coli infections." (PMID 36552020, 2022).
HCMV infection (46 papers, 2010 to 2025). "After kidney transplantation, the NFKB1 promoter polymorphism (-94ins/delATTG) is related to susceptibility to cytomegalovirus infection." (PMID 36330810, 2022). "Of note, the NFKB1 -94ins/delATTG promoter polymorphism was recently associated with a higher risk of CMV infection." (PMID 33673169, 2021). "Regarding the underlying NFKB1 genotype, homozygous insertion carriers had the highest risk for CMV infection in comparison to heterozygous and homozygous deletion carriers." (PMID 33673169, 2021). "Multivariable proportional hazards model showed that the NFKB1 promoter polymorphism was an independent risk factor for CMV infection with a 0.61-fold lower risk (95%CI: 0.38–0.97) for heterozygous and homozygous deletion allele carriers." (PMID 33673169, 2021). "In conclusion, our findings could confirm the reported association of the NFKB1 -94ins/delATTG promoter polymorphism with the risk of CMV infection after kidney transplantation." (PMID 33673169, 2021). "Hence, the NFKB1 -94ins/delATTG promoter polymorphism seems to be a promising candidate supporting the prediction of CMV infection and enrichment of risk-adapted anti-CMV strategies in terms of precision medicine." (PMID 33673169, 2021). "Therefore, we performed this retrospective study for evaluating and confirming the association of the NFKB1 -94ins/delATTG promoter polymorphism with the risk of CMV infection in kidney transplant patients in our much larger patient population." (PMID 33673169, 2021). "Hence, we can confirm an association of the -94ins/delATTG NFKB1 promoter polymorphism with the risk for CMV infection, in accordance with the findings of Leone and colleagues." (PMID 33673169, 2021). "The apparently pivotal role of the -94ins/delATTG NFKB1 promoter polymorphism is not surprising, since it is well known that NF-κB is highly involved in the pathogenesis of CMV infection." (PMID 33673169, 2021).
myeloid leukemia (46 papers, 2006 to 2026). A clonal proliferation of myeloid cells and their precursors in the bone marrow, peripheral blood, and spleen. "Our analysis suggests that a direct link from NFKB1 to F3 (coagulation factor III/Tissue factor) is among the top links that discriminate between the two types of myeloid leukemia." (PMID 16670008, 2006).
fibrosarcoma (45 papers, 2008 to 2026). A malignant mesenchymal fibroblastic neoplasm affecting the soft tissue and bone. "More directly, the inhibitory function of MDSCs was strongly reduced in Nfkb1−/− animals- though their number was increased in the tumor bed- resulting in the reduced growth of transplanted murine fibrosarcoma." (PMID 33572260, 2021).
osteopetrosis (43 papers, 2006 to 2025). Osteopetrosis, also known as marble bone disease, is a descriptive term that refers to a group of rare, heritable disorders of the skeleton characterized by increased bone density on radiographs. "NF-κB induction is a critical event as the genetic disruption of nfκb1 and nfκb2 genes coding for p50 and p52 transcription factors in mice leads to osteopetrosis due to impaired osteoclast differentiation." (PMID 23861901, 2013).
primary immunodeficiency (41 papers, 2010 to 2025). "None of the family members possessed both gene mutations, suggesting that the simultaneous mutations of C6 and NFKB1 caused primary immunodeficiency in the patient and resulted in recurrent opportunistic infections." (PMID 39823049, 2024). "As part of this review series focused on EBV-related primary immunodeficiencies, we discuss the current clinical and molecular understanding of monoallelic NFKB1 germline mutations with special focus on the emerging context of EBV-associated disease." (PMID 29403474, 2017). "Interestingly, the NF-κB pathway is activated in CSF memory B cells from MS patients and a mutation in the NFKB1 gene has been implicated in a primary immunodeficiency characterized by poor control of EBV and lymphoproliferation." (PMID 34305896, 2021). "Having analyzed sequencing panel data from 270 patients with primary immunodeficiency falling under CVID/late-onset CID, we conclude that NFKB1 alterations are the most common monoallelic cause of antibody deficiency in our cohort." (PMID 31803180, 2019). "NKG2D and NFκB1 are affected by primary immunodeficiencies with EBV pathologies that result from mutations in the magnesium transporter MagT1 and the transcription factor NFκB1, respectively." (PMID 29225606, 2017). "In-depth immune evaluation revealed antibody deficiency syndrome with dysregulated B cell development in family members carrying the CXCR4 variant, whereas P4 – who carried only the NFKB1 variant – showed a profound antibody deficiency and immunologic markers consistent with CVID." (PMID 40909287, 2025). "However, little is known about how NFκB1 defects or primary immunodeficiency (PID) complicate pregnancy." (PMID 34307247, 2021). "Notably, mice heterozygous for Nfkb1 do not develop the primary immunodeficiency found in humans with NFKB1 haploinsufficiency, suggesting key differences in the role of NFKB1 in humans and mice." (PMID 34721373, 2021).
enteritis (40 papers, 2010 to 2025). Inflammation of the small intestine. "There has been one report on a patient with coeliac-like disease and a NFKB1 mutation and on one patient with enteritis and giardiasis, which puts our findings of one patient with a coeliac-like histology into context." (PMID 34599484, 2022).